ARMCX4 (armadillo repeat containing X-linked 4)
Synonyms: MGC40053; GASP4; CXorf35
Tractability: Antibody: UniProt predicts a signal peptide or a membrane-spanning region. PROTAC: its protein half-life has been measured.
Gene: Protein-coding gene on chromosome X (101,418,287 to 101,533,459, forward strand). Ensembl gene ENSG00000196440.
Subcellular location: Membrane
Subcellular location (Human Protein Atlas): Nucleoplasm; Vesicles
Gene Ontology:
Cellular component: membrane
Homologues: Orthologues: macaque ARMCX4 (94% identical), rabbit ARMCX4 (68% identical), pig ARMCX4 (64% identical), dog ARMCX4 (63% identical), rat Armcx4 (59% identical), mouse Armcx4 (59% identical), zebrafish armc10 (4% identical), tropical clawed frog armc10 (4% identical), Caenorhabditis elegans Y67A10A.7 (3% identical). Paralogues in human: GPRASP1 (14% identical), GPRASP2 (9% identical), ARMCX2 (8% identical), ARMCX5 (7% identical), ARMCX1 (7% identical), ARMCX3 (7% identical), ARMC10 (6% identical), GPRASP3 (5% identical), ARMCX6 (4% identical), ARMC12 (2% identical).
Diseases named in the same sentence as ARMCX4 in open-access papers:
ARMCX4 is named in the same sentence as 10 diseases in open-access papers, as found by Europe PMC text mining. Sharing a sentence is not in itself a finding about the gene and the disease. The quoted sentences say what the papers report.
congenital myasthenic syndrome (1 paper, 2021). Congenital myasthenic syndrome (CMS) is a group of genetic disorders of impaired neuromuscular transmission at the motor endplate characterized by fatigable muscle weakness. "ARMCX4 interacts with DPAGT1, which suggests that ARMCX4 inhibits congenital myasthenic syndrome (CMS), GD, male infertility, and neonatal maxillofacial deformities by interacting with DPAGT1." (PMID 34912852, 2021).
endometrial cancer (1 paper, 2023). Primary or metastatic malignant neoplasm involving the endometrium (mucous membrane that lines the endometrial cavity). "On the other hand, Chang and his colleagues, in the year 2017, performed whole exome sequencing and identified novel mutations in several potential cancer drivers and passenger cancer genes ARMCX4 gene is one among them, which is responsible for causing endometrial cancer." (PMID 37994325, 2023).
gastric tumors (1 paper, 2020). "ARMCX1, ARMCX2, and ARMCX4 were lowly expressed in primary gastric tumors and has a high expression in normal gastric tissues." (PMID 32685472, 2020).
male infertility (1 paper, 2021). The inability of the male to effect fertilization of an ovum after a specified period of unprotected intercourse. "In fact, it has been reported that ARMCX4 promotes the differentiation of spermatogonial stem cells (SSCs), and ARMCX4 mutations can cause male infertility." (PMID 34912852, 2021). "It has also been reported that ARMCX4 promotes the differentiation of SSCs, and ARMCX4 mutations can cause male infertility." (PMID 34912852, 2021). "ARMCX4 interacts with DPAGT1, which suggests that ARMCX4 inhibits male infertility by interacting with DPAGT1." (PMID 34912852, 2021).
Parkinson disease (1 paper, 2021). A progressive degenerative disorder of the central nervous system characterized by loss of dopamine producing neurons in the substantia nigra and the presence of Lewy bodies in the substantia nigra and locus coeruleus. "ARMCX4, also known as GASP-4, is one of the highly dysregulated priority genes in brains of Parkinson’s disease." (PMID 34899276, 2021).
thyroid (1 paper, 2021). "Finally, when manually scrutinizing mutated genes and comparing to findings in the COSMIC database, case 3 (with no credible thyroid-related driver event) was found to exhibit a somatic ARMCX4 mutation (c.5474C>T, p.Ala1825Val) in the primary tumor." (PMID 33827048, 2021).
thyroid cancer (1 paper, 2021). "Although not a tier 1 CGC gene, ARMCX4 mutations have been reported in 43 thyroid cancer specimens out of >1000 sequenced cases (COSMIC study COSU676)." (PMID 33827048, 2021).
ARMCX4 also shares sentences with these, for which no sentence is quoted: cancer (1 paper); colon cancer (1); tumor (1).